BRAF (B-Raf proto-oncogene, serine/threonine kinase)
Diseases named in the same sentence as BRAF in open-access papers (continued):
Sharing a sentence is not in itself a finding about the gene and the disease.
melanoma (continued). "Although mutant-specific inhibitors like vemurafenib and GSK2118436 are predicted to be equally efficacious against a variety of V600 mutants, clinical trials with the approved BRAF inhibitor, Vemurafenib, have thus far have focused on enrolling only those with V600E mutant melanoma." (PMID 22536370, 2012). "Promising biomarkers for melanoma include KIT and BRAF gene mutations." (PMID 22123319, 2011). "Alterations in BRAF regulated signaling pathways that could affect actin organization and melanoma invasion were then evaluated." (PMID 21917148, 2011). "In BRAF mutant melanoma cells, inhibition of BRAF using small molecule inhibitors and siRNA knockdown leads to the induction of apoptosis via a mechanism involving the decreased phosphorylation of BAD at Ser-75, an upregulation of BMF and an increase in BIM expression." (PMID 21505227, 2011). "Unlike primary melanomas, >15% of metastatic melanoma samples with BRAF mutations exhibit amplification of CCND1." (PMID 21479172, 2011). "Even though BRAF mutations occur more frequently in melanomas linked to sun exposure, the BRAF gene does not contain C>T or CC>TT transitions typical of UV-induced damage." (PMID 21827678, 2011). "In a melanoma study of 21 patients who received a sufficiently high dose of vemurafenib, 5 without the V600E BRAF mutation did not respond to the drug; however, of 16 patients with the mutation, 9 responded to vemurafenib and 7 did not." (PMID 22123319, 2011). "Curtin and colleagues showed that primary melanomas arising from chronically sun-damages skin and mucosal sites, the latter of which typically do not harbor BRAF and NRAS mutations, have increased CCND1 copy number." (PMID 21479172, 2011). "Whether combinations of selective RAF inhibitors in patients with BRAF mutant melanoma will result in better outcomes remains to be investigated." (PMID 21139585, 2011). "Finding the right combination of therapies to effectively treat metastatic melanoma remains one of the biggest challenges in melanoma research, especially in melanoma cells that do not harbor the BRAF V600E mutation." (PMID 21378407, 2011). "These melanomas are resistant to BRAF inhibitors highlighting the need for combination therapy." (PMID 21479172, 2011). "Other investigators have provided convincing evidence that the effects of targeted inhibitors on melanoma cell lines is different in 2-dimension and 3-dimension models, with higher resistance to BRAF inhibitors in 3 dimension models mediated by the PI3K/AKT pathway." (PMID 22194965, 2011). "In BRAF mutant melanoma, 74–90% are V600E and 16–29% are V600K mutations." (PMID 21139585, 2011). "Interestingly, two of 22 patients with wild-type BRAF had a PR with treatment, suggesting that some melanoma tumors are dependent on ERK/MAP kinase signaling despite the absence of a BRAF mutation." (PMID 22175026, 2011). "Importantly, the correlation between cytoskeletal remodeling and drug insensitivity does not implicate prominent actin stress fibers as a predictive factor or "biomarker" for melanoma resistance to BRAF inhibition." (PMID 21917148, 2011). "In patients with mutant BRAF melanoma a combination of a selective RAF inhibitor with an HSP90 inhibitor may, therefore, inhibit multiple pathways involved in resistance." (PMID 21139585, 2011). "In addition to its effects upon cell growth, mutant BRAF also contributes to the oncogenic phenotype of melanoma cells through both down regulation of apoptotic signals and enhancement of cell invasion." (PMID 21505227, 2011). "Autoantibodies to the BRAF protein have been reported in melanoma patients and patients with RA." (PMID 22174938, 2011). "Mutations of the BRAF gene are usually absent in melanomas occurring in this region as well as in other sun-protected regions." (PMID 21827678, 2011).
melanoma (continued). "It has recently been shown that the phospho-ERK staining was not correlated with the mutational status of NRAS and/or BRAF in melanoma tissues, and that cultured BRAF-mutant melanoma cells downregulated RAS/RAF/MEK/ERK activation when cultured at high densities or under non-adherent conditions." (PMID 21224857, 2011). "Thus, the results indicate that most primary melanomas are polyclonal, consisting of BRAF-mutant, as well as BRAF-wild-type tumour cells." (PMID 21224857, 2011). "Likewise, BRAF, a major downstream effector of KRAS, is also considered an oncogene whose activating mutations appear in 70% of human malignant melanomas and in about 12-18% of human colon cancers." (PMID 21943101, 2011). "Just as pimozide shows enhanced efficacy in CML when combined with BCR/ABL inhibitors, pimozide may be particularly useful in melanoma when combined with BRAF inhibitors." (PMID 21680956, 2011). "The behaviour of mutant BRAF melanomas in murine xenograft models supported these preclinical findings and confirmed mutant BRAF as an attractive target for melanoma therapy, particularly as it occurs in at least half the tumour population, and does not occur in normal cells." (PMID 21139585, 2011). "A particularly important point in the tumorigenesis of acral melanomas that is different from other subtypes of melanomas such as Non-CSD melanomas is that BRAF mutations occur at lower frequencies in acral melanomas." (PMID 21911917, 2011). "Taken together, these data indicate the importance of BRAF as a therapeutic target in melanoma." (PMID 21479172, 2011). "Thus, BRAF mutant melanomas signal exclusively through MEK and subsequently ERK leading to oncogenesis." (PMID 22175026, 2011). "No anti-proliferative or cytotoxic effects were observed in melanoma cell cultures that lacked the BRAF mutation." (PMID 21505227, 2011). "The V600E mutation (T1799A) in exon 15 of the BRAF gene was present in the heterozygous state in the melanoma sample, but it was absent in non-tumour DNA obtained from peripheral blood of the same melanoma patient." (PMID 21827678, 2011). "Notably, we now identify the BRAF V600E mutation in approximately 60% of grade II PXA, a similar mutation rate as seen in malignant melanoma." (PMID 21479234, 2011). "While there is great hope that these drugs will successfully halt progress in patients with BRAF mutant melanomas, emerging data suggests that they might be counterproductive for patients with wildtype BRAF." (PMID 21479172, 2011). "Among the several genetic alterations governing melanoma initiation and progression so far identified, the serine/threonine-specific protein kinase BRAF is thought to be a key player because it is activated by somatic mutations in 50–70% of cutaneous melanomas." (PMID 21224857, 2011). "A phase-II study of GSK 2118436 is currently underway as salvage therapy in mutant BRAF metastatic melanoma and a phase-I study has commenced of GSK 2118436 in combination with the MEK-inhibitor, GSK1120212, (NCT01072175) in BRAF mutant melanoma patients, a strategy of tandem MAPK inhibition." (PMID 21139585, 2011). "The success of our current clinical trials with single agent Riluzole and the combination of Riluzole with Sorafenib would be beneficial to patients with mGlu1 positive melanomas regardless of common mutations like BRAF V600E." (PMID 24619402, 2010). "The BRAF V600E mutation has been reported to be correlated with sensitivity to MEK inhibitors and has been used as a major criterion for recruiting patients into a clinical trial of MEK inhibitors in melanoma patients." (PMID 21124782, 2010). "The finding that dual BRAF/MEK inhibition prevents the onset of resistance in our in vitro melanoma models suggests that MEK inhibitors may be of use in managing resistance to BRAF inhibitors and may delay or even prevent the onset of resistance in some cases." (PMID 20531415, 2010).
melanoma (continued). "Conversely, congenital nevi in children frequently harbor RAS, but not BRAF mutations and are associated with an increasing risk of melanoma development." (PMID 21170325, 2010). "BRAF, a mitogenic Ser/Thr kinase in the MAPK/ERK pathway, has an activating mutation, V600E, in at least 50% of melanomas and is thought to be a central oncogenic driver in melanoma." (PMID 24212610, 2010). "Endogenous BRAF was immunoprecipitated from melanoma cells and western blotted for endogenous CRAF." (PMID 20141835, 2010). "Resistance to BRAF inhibitors is an emerging problem in the melanoma field." (PMID 20531415, 2010). "Inhibition of the activated MAPK pathway through BRAF silencing with RNA interference results in apoptosis of melanoma cell lines carrying the BRAFV600E mutation and regression of BRAFV600E melanoma xenografts, suggesting that BRAF is an attractive drug target." (PMID 21206909, 2010). "Responses were observed in an unprecedented 70% of patients, and there is now hope that small molecule BRAF inhibitors could constitute a major new melanoma therapy." (PMID 20531415, 2010). "As expected, all four drugs blocked ERK activity in BRAF mutant A375 melanoma cells." (PMID 20141835, 2010). "Interestingly, in agreement with the proliferation and viability results, UACC903 BRAF mutant melanoma cells showed the higher accumulation of cells in G1 phase." (PMID 20529342, 2010). "Interestingly, mutant BRAF, which is present in almost 70% of all melanomas, shows marked dependency on Hsp90 and is degraded by 17-AAG treatment, while WT BRAF activated by NRAS is also Hsp90 dependent." (PMID 21037799, 2010). "Inhibition of mutant BRAF is an attractive therapeutic approach for the treatment of melanoma." (PMID 20667740, 2010). "Further analysis of nevi (benign accumulations of melanocytes, commonly known as moles) revealed that the majority of nevi also had BRAF mutations, suggesting that BRAF mutations alone are not sufficient to promote melanoma." (PMID 20230482, 2010). "Nearly 60% of BRAF and 30% of N-RAS are mutated in melanomas." (PMID 24281076, 2010). "BRAF-mutant tumors have been reported to have a worse prognosis than, for example, NRAS mutants, another oncogenic mutation that is thought to drive melanoma formation in a smaller subset of tumors." (PMID 24212610, 2010). "Interestingly, BRAF mutant melanoma cell lines (UACC903 and Colo829) showed the highest sensitivity to MTA treatment, where concentrations of 10 μM of MTA reduced proliferation up to 70%." (PMID 20529342, 2010). "The results demonstrated that drug response can be modulated by the BRAF genotype but is not affected by mutations in NRAS or downregulation of PTEN in BRAFWT melanoma cells isolated from advanced lesions." (PMID 20149136, 2010). "Increasing concentrations of PLX4720 (1 h) inhibited pERK signalling in three BRAF-mutated melanoma cell lines (WM35, WM164 and 1205Lu), but not an NRAS-mutated cell line (WM1346)." (PMID 20531415, 2010). "Oncogenic BRAF and N-RAS mutations are frequent in malignant melanoma." (PMID 24281076, 2010). "Activating mutations in NRAS and β-catenin, or loss of PTEN did not affect the responses of BRAFWT melanoma cells to this BRAF inhibitor." (PMID 20149136, 2010). "The effect was noted in both BRAF mutant SKMEL28 and BRAF wildtype CHL-1 melanoma cells." (PMID 21037799, 2010). "This is in agreement with findings from previous studies in larger melanoma cell line panels showing no dependence of sensitivity to 17-AAG on BRAF mutation status." (PMID 21037799, 2010). "If an upregulated MAPK pathway is in fact the most important mechanism that drives tumor proliferation in melanomas carrying the BRAFV600E mutation, the high selectivity and potency of these new agents should provide more insight into the role of BRAF as a critical therapeutic target in melanoma." (PMID 21206909, 2010).
melanoma (continued). "Five objective responses were observed among 42 patients with BRAF V600E mutations (12% objective response rate), indicating that a subset of BRAF mutant melanomas may be sensitive to this agent." (PMID 19156138, 2009). "The aim of the present study was to test the hypothesis that NFAT may be an important downstream target of oncogenic BRAF in melanoma and that NFAT is involved in regulating COX-2 expression." (PMID 19724275, 2009). "The discovery of BRAF mutations in melanoma has not yet translated into clinical success, suggesting that BRAF/MEK inhibitors will need to be combined with other agents." (PMID 19156138, 2009). "Identifying that NFAT functions downstream of mutant BRAF in melanoma, raises the possibility that NFAT may be similarly activated in other BRAF-mutated cancers." (PMID 19724275, 2009). "Even in melanomas that are the most sensitive, prolonged BRAF/MEK inhibitor treatment may lead to the rapid acquisition of drug resistance." (PMID 19156138, 2009). "The presence of BRAF mutations in nevi strongly suggests that BRAF activation is necessary but not sufficient for the development of melanoma (also known as melanomagenesis)." (PMID 19828018, 2009). "There is evidence that PLX-4032 and its tool-compound counterpart PLX-4720 induces some limited apoptosis in melanoma cell lines with the V600E mutation but not in those that are BRAF wild type." (PMID 19156138, 2009). "As selective BRAF targeted compounds have relatively few off-target effects, it is now possible to assess the effects of specific pharmacological inhibition of BRAF in melanoma." (PMID 19156138, 2009). "KIT mutations are mutually exclusive with BRAF and NRAS, and may identify a subset of melanoma that preferentially respond to the KIT inhibitors such as imatinib (Gleevec) or sorafenib." (PMID 19949544, 2009). "In experimental systems, the role of BRAF in melanoma seems convincing." (PMID 19156138, 2009). "To test this hypothesis we starved BRAF mutant melanoma cells under serum free and low glucose conditions in the presence or absence of the Mek1/2 inhibitor U0126, and investigated the activation of LKB1-AMPK-mTOR pathway." (PMID 19274086, 2009). "Here we describe another intriguing aspect of MITF regulation by oncogenic BRAF in melanoma cells." (PMID 18628967, 2008). "Furthermore, the MITF gene is amplified in 10–15% of melanomas in which BRAF is mutated, supporting the view that continued expression of MITF is essential in melanoma cells." (PMID 18628967, 2008). "Expression profiling of melanoma cell lines with or without the BRAF mutation revealed signature genes which allowed for the classification of cells as mutant or wild-type." (PMID 19517027, 2008). "Thus BRN2 re-expression is important for melanoma progression and we have previously shown that BRN2 is a target of oncogenic BRAF in melanoma cells." (PMID 18628967, 2008). "Thus, in apparent contradiction to our previous findings, these data suggest that ERK activation is necessary for MITF expression in melanoma cells expressing oncogenic BRAF." (PMID 18628967, 2008). "Furthermore, we found that BRAF depletion resulted in reduced MITF mRNA expression in melanoma cells." (PMID 18628967, 2008). "This suggests that the MITF promoter is regulated differently by oncogenic BRAF in mouse and human cells, but it should be mentioned that in contrast to humans, somatic mutations in BRAF do not appear to be a feature of mouse melanomas." (PMID 18628967, 2008). "Sorafenib is being studied in combination with cytotoxic chemotherapeutic agents, such as doxorubicin in melanoma where, despite a high frequency of BRAF mutations, this agent does not appear to be majorly biologically active." (PMID 17179987, 2007). "Of the BRAF-targeted agents, Sorafenib has progressed to approval by the United States Food and Drug Administration for therapy of renal cell carcinoma and is under evaluation for melanoma, thyroid cancer and other malignancies." (PMID 17179987, 2007).
melanoma (continued). "They interpret these findings to mean that BRAF mutations are not involved in the initiation of the majority of melanoma, but rather play a role later in progression." (PMID 15613230, 2004). "Forty to eighty percent of melanoma tumors have activating mutations in BRAF although the clinical importance of these mutations is not clear." (PMID 15613230, 2004). "We found that patients with tumors harboring a BRAF mutation were more likely to have metastasis to the liver and tended to have more organs involved with melanoma than patients without mutations." (PMID 15613230, 2004). "Although there were too few of these patients for a meaningful statistical analysis, this observation is consistent with a recent report indicating that mucosal melanomas did not harbor BRAF mutations." (PMID 15613230, 2004). "However, in the population of BRAF mutation melanoma, irrespective of prior treatment with BRAF/MEK inhibitors, the ORR of combination therapy was only about 10%." (PMID 41492362, 2026). "C-MET is influenced by NRAS mutations, as NRAS-mutated melanomas, for instance, show higher activation of the C-MET pathway and increased sensitivity to C-MET inhibitors compared to BRAF (human gene that encodes a protein called B-Raf) mutated or wild-type melanomas." (PMID 41563267, 2026). "NF1‐mutant melanomas are clustered within elderly individuals and chronically sun‐exposed skin, and they exhibit a distinctive molecular profile marked by high mutation burden and the absence of BRAF or NRAS mutations." (PMID 41492362, 2026). "Although access to systemic treatments expanded during the study period, initially with ipilimumab (2012) and later with targeted therapies such as vemurafenib and cobimetinib for BRAF V600 mutated melanoma (2016), this did not translate into a clear increase in melanoma registrations in SACT." (PMID 41534884, 2026). "Among the mutations in melanoma, the most frequently observed are the ones with the presence of the BRAF proto‐oncogene serine/threonine‐protein kinase B‐raf (BRAF) or the NRAS proto‐oncogene GTPase (NRAS) activating mutations—accounting for about 50% and 20%–25% of melanomas, respectively." (PMID 41546170, 2026). "Moreover, recent evidence suggests that the pirin-MRTF axis may be influenced by upstream oncogenic signalling events, particularly those associated with BRAF or NRAS mutations, prevalent in melanoma." (PMID 40740997, 2025). "Subsequently, to investigate the impact of TRIM63 on IRF-8, we conducted TRIM63 depletion, which resulted in an increase in IRF-8 protein levels specifically in melanoma cells harboring BRAF V600E mutation, while no such effect was observed in cells with wild-type BRAF." (PMID 41315179, 2025). "BRAF mutations are not typically associated with primary retinoblastoma but could be relevant in the context of secondary cancers, particularly melanoma, in patients with hereditary retinoblastoma." (PMID 40317918, 2025). "Furthermore, in vivo studies demonstrated that TRIM63 overexpression exerted effects solely on melanoma cells with BRAF mutations rather than those with wild-type BRAF." (PMID 41315179, 2025). "However, the glucose utilization was not significantly different between control and treated cells in vitro in this study, which suggest the BRAF/MEK dual inhibition might act on downstream steps of glycolysis in melanoma cells." (PMID 39984334, 2025). "As a result, our findings may not be fully generalizable to the entire melanoma spectrum, particularly for patients harboring BRAF mutations (although 128 BRAF:V600 cases are a sufficient number to inform model training)." (PMID 40075562, 2025). "While AR variants have not been linked directly to the risk of malignant melanoma, AR may play a role in melanoma treatment since it has been shown that AR blocking is mediating a better response to BRAF/MEK inhibition." (PMID 40072281, 2025).